STAT1 (signal transducer and activator of transcription 1)
Diseases named in the same sentence as STAT1 in open-access papers (continued):
Sharing a sentence is not in itself a finding about the gene and the disease.
tuberculosis (19 papers, 2009 to 2026). A chronic, recurrent infection caused by the bacterium Mycobacterium tuberculosis. "One was an IL2RB1 gene mutation that leads to susceptibility to tuberculosis, and the other was a JAK3 gene mutation that is associated with severe combined immunodeficiency and a STAT1 gene mutation that also increases susceptibility to tuberculosis." (PMID 38678116, 2024). "In association with this, the expression pattern of many STAT-1 mediated proinflammatory pathway genes, including Cxcl10 (IP-10) and Ccl20 that are considered biomarkers of active Tb disease, were also downregulated in the ΔbfrB vaccinated mice lungs." (PMID 26339659, 2015). "In this study, we found that cyclosporin can upregulate the expression of PSMB9 and STAT1, which may be one of the mechanisms of cyclosporin-induced increased risk of activation of tuberculosis disease." (PMID 37340462, 2023). "In order to investigate the mechanisms of these responses, we used nebulized rIFN-γ1b in eleven drug-sensitive tuberculosis patients, and found an increase in signaling molecules STAT-1, IRF-1 and IRF-9." (PMID 19753300, 2009). "Interestingly, while STAT1 also emerges in the Tier-1 network in pneumonia, it makes a different set of interactions in pneumonia as compared to tuberculosis." (PMID 28649431, 2017). "Over the years, several studies have identified genetic polymorphisms associated with different molecules in the IFN-γ induction pathway, especially T-Bet, STAT1, and IFNGR1/IFNGR2, and these polymorphisms seem to influence susceptibility to several infectious diseases, including tuberculosis." (PMID 26000298, 2015). "Moreover, STAT1 is a biomarker of immune infiltration changes after anti-tuberculosis treatment." (PMID 37026000, 2023). "Many interferon pathway-related genes, including STAT1,GBP1,GBP5, IFI44, IFIH1, FITM3, have been described in whole-blood transcriptome studies of tuberculosis." (PMID 36059536, 2022). "Activation of STAT1 and c-JUN is a possible mechanism in macrophages for patients to survive against active tuberculosis." (PMID 32290250, 2020). "In the current study, six genes (IFITM1, IRF9, MX1, OAS1, STAT1, and STAT2) of the “host response signature network” are significantly overlapping with the “human immune response to tuberculosis” pathway with p-value 1.57e-8." (PMID 33362771, 2020). "In summary, we found that upregulation of hBD1 in AEC-II cells is mediated by CEBPB activated by ERK1/2 following Mtb infection, but not by STAT1, and promotes anti-tuberculosis effect." (PMID 38397085, 2024).
atopic dermatitis (18 papers, 2018 to 2025). "Phosphorylation of STAT-1 has been reported to induce atopic dermatitis by including a Th2 responses." (PMID 36793948, 2023). "These cytokine expressions were requested by activation of signaling molecules such as MAPKs, STAT-1, and NF-κB, which play essential roles in several inflammatory responses, including atopic dermatitis." (PMID 36793948, 2023). "NFκB-p65 and STAT-1 are transcription factors that are critically involved in atopic dermatitis-related signaling in TNF-α/IFN-γ–stimulated HaCaT cells." (PMID 29932162, 2018). "STAT1 drives to Th2 responses, leading to the development of atopic dermatitis." (PMID 36158872, 2022). "It is well known that the activation of the degradation of IκB-α, STAT-1, and MAPK in keratinocytes are associated with AD, and keratinocytes stimulated with TNF-α/IFN-γ are widely used for verification of the in vitro efficacy of anti-atopic dermatitis." (PMID 34500860, 2021). "Isoliquiritin downregulates the JAK/STAT signaling pathway by inhibiting the phosphorylation of JAK2, STAT1, STAT3, and STAT5, thereby regulating immune and inflammation responses and contributing to the treatment of atopic dermatitis." (PMID 40657637, 2025).
esophageal cancer (18 papers, 2014 to 2025). A primary or metastatic malignant neoplasm involving the esophagus. "For example, it needs further research on how RNF168 reduces the polyubiquitination of STAT1 and how it affects the protein of the Wnt/β-catenin signaling pathway to promote the progression of esophageal cancer." (PMID 36771081, 2023). "Rescue experiments in PD-L1 knockdown cells further confirmed that STAT1/IFIT2 pathway was involved in the PD-L1 mediated EMT of esophageal cancer cells." (PMID 35107757, 2022). "Our present work reveals a novel mechanism of how PD-L1 regulates EMT of cancer cells, namely STAT1/IFIT2 signal pathway is required in PD-L1 mediated EMT in human esophageal cancer." (PMID 35107757, 2022). "Collectively, our current findings provided a novel mechanism underlying the effects of PD-L1 on EMT of cancers, showing that STAT1/IFIT2 signaling pathway was required in PD-L1-mediated EMT in human esophageal cancer." (PMID 35107757, 2022). "Herein, we further investigated the clinical significance and biological role of IFIT2 in human esophageal cancer, and confirmed that STAT1/IFIT2 pathway was involved in the PD-L1-mediated EMT of esophageal cancer cells." (PMID 35107757, 2022). "The STAT1/IFIT2 signal pathway was activated when PD-L1 was knockdown in human esophageal cancer cells." (PMID 35107757, 2022). "Our present findings provided a novel mechanism underlying the effects of PD-L1 on EMT of cancer cells, showing that STAT1/IFIT2 signaling pathway was required in PD-L1-mediated EMT in human esophageal cancer." (PMID 35107757, 2022). "Here, we report an important function for RNF168 protein in supporting oesophageal cancer growth and invasion by stabilizing STAT1 protein." (PMID 30506884, 2019). "This study provides a novel mechanism that RNF168 modulates JAK‐STAT signalling via regulating STAT1 protein stability in oesophageal cancer." (PMID 30506884, 2019). "Moreover, epidermal growth factor (EGF) has also been reported to inhibit tumor cell proliferation in esophageal cancers via STAT1 activation, paralleling the signaling of IFN-γ that induces apoptosis in esophageal tumor cells." (PMID 40909948, 2025). "Moreover, they lead to mutations in the signal transducer and activator of the transcription 1 [STAT1] gene that induces esophageal cancer." (PMID 40258837, 2025). "In our present study, we found that modification of PD-L1 expression could significantly regulate the STAT1/IFIT2 signaling pathway in human esophageal cancer cells." (PMID 35107757, 2022). "Considering the oncogenic role of STAT1 in oesophageal cancer, the RNF168 may be a promising new therapeutic target for oesophageal cancer therapy." (PMID 36042206, 2022). "Immuno‐precipitation shows that RNF168 associates with STAT1 in oesophageal cancer cells." (PMID 30506884, 2019). "Regarding the phosphorylation of STAT1 in esophageal cancers, patients exhibiting low ERK and elevated STAT1 expression levels demonstrate improved survival outcomes." (PMID 40909948, 2025). "Ring finger protein 168 repressed STAT1 polyubiquitination and degradation to upregulate JAK-STAT1 signaling and the downstream functional genes, contributing to the growth and invasion of esophageal cancer." (PMID 38273295, 2024). "The STAT1 gene was highly expressed in most tumors, including cholangiocarcinoma (CHOL), colon adenocarcinoma (COAD), esophageal carcinoma (ESCA), liver hepatocellular carcinoma (LIHC), pancreatic adenocarcinoma (PAAD), READ, and stomach adenocarcinoma (STAD)." (PMID 36061181, 2022). "To uncover the mechanism through which genistein affects cyclical distribution and apoptosis in esophageal cancer cells, we tested the expression levels and phosphorylation levels of JAK1, JAK2, STAT1 and STAT3 in Eca-109 cells." (PMID 32276266, 2020). "We previous found that STAT1 plays a tumor suppressor role in esophageal cancer, and ERK expression was inversely correlated with STAT1." (PMID 29855346, 2018).
esophageal cancer (continued). "Consequently, targeted inhibition of ERK represents a novel therapeutic strategy for esophageal cancers, potentially realized through the activation of the IFN-γ/STAT1 pathway." (PMID 40909948, 2025). "In esophageal cancer, activation of P4HA1 by STAT1 transcription could boost cell growth and survival." (PMID 38250070, 2023). "A recent study in squamous cells of an esophagus carcinoma model shows that these cells present increased STAT3 phosphorylation and signaling due to a constitutive activation of ERK, which promotes the degradation of STAT1 via the proteasome." (PMID 34925319, 2021). "RNF168 may stabilize STAT1 protein, which is a core component of the JAK-STAT signaling pathway, by inhibiting the polyubiquitination of STAT1, and thus promote the proliferation and invasion of esophageal cancer cells by activating the JAK-STAT signaling pathway." (PMID 36771081, 2023).
HIV-1 infection (18 papers, 2012 to 2025). The type species of lentivirus and the etiologic agent of acquired immunodeficiency syndrome (AIDS). "TRAIL protein is produced after HIV-1 infection in monocytes due to the IFNα/β-mediated activation of the STAT1 signaling cascade, and has been shown to cause apoptosis in several cell lines during HIV-1 infection." (PMID 25170834, 2014). "This increase of the p-STAT1-GLS1 promoter DNA complex upon HIV-1 infection was associated with a four-fold and two-fold increase of p-STAT1 and STAT1 protein levels, respectively, compared with uninfected cells." (PMID 22479354, 2012). "Furthermore, sustained upregulation of this ISG cluster, including ISG15, MX1, OAS1 and STAT1, is a hallmark of untreated HIV-1 infection." (PMID 41226717, 2025). "Concurrently, HIV-1 infection retains unphosphorylated STAT1 within the nucleus, preventing its export to the cytoplasm for subsequent phosphorylation." (PMID 41009690, 2025). "In primary myeloid cells, both HIV-1 infection and the viral accessory protein Vpr have been shown to activate this pathway, resulting in increased STAT1 phosphorylation together with coordinated induction of ISG15, MX1, IFIT3/IFI44L, and OAS genes." (PMID 41226717, 2025). "HIV-1 infection profoundly dysregulates STAT1, with major implications for immune function and disease pathogenesis." (PMID 41009690, 2025). "In the context of HIV-1 infection, STAT-1 was shown to regulate HIV-1 promoter activity and was implicated in the immunopathogenesis of HIV-1 infection and its inflammatory responses." (PMID 37840143, 2023). "Altogether, these findings uncover the IFN-I/STAT1/Siglec-1 axis as a mechanism established by Mtb to exacerbate HIV-1 infection in myeloid cells, and call for the need to further investigate this signaling pathway in TB pathogenesis." (PMID 32223897, 2020). "It has been shown that the STAT1 pathway plays an important role in the pathogenesis of HIV-1 infection; indeed, activation of the STAT1 pathway by HIV-1 Vpr is demonstrated in this study." (PMID 25170834, 2014). "In our previous study we demonstrated that IFN-α and HIV-1 infection specifically activated the human GLS1 promoter through STAT1 phosphorylation and activation." (PMID 24086752, 2013). "More importantly, HIV-1 infection induced STAT1 to bind to the GLS1 promoter thereby leading to glutamate overproduction." (PMID 22479354, 2012). "This was based on findings showing that the HIV-1 infection of macrophages decreased intracellular tyrosine-phosphorylated STAT-1 (STAT-1PY) levels due to STAT-1 interaction with cystatin B, sequestering STAT-1 in the cytoplasm and preventing its phosphorylation." (PMID 38542221, 2024). "AhR activation can have a variety of effects on cells that could plausibly lead to inhibition of HIV-1 infection, including STAT1 activation (that might active expression of antiviral genes) or inhibition of cell cycle progression." (PMID 30132758, 2018). "Because pSTAT1 binds with sites 2/3 and 5/6 and the binding is increased following IFN-α treatment or HIV-1 infection, the potential involvement of unphosphorylated STAT1 in the regulation of GLS1 promoter activity may need further investigations." (PMID 24086752, 2013). "Therefore, T cells from both HIV-1- and HTLV-2-infected individuals share a constitutive priming for IFN-γ secretion and, consequently, for STAT1 activation; in contrast, only HIV-1 infection is characterized by activation of STAT5Δ in vivo." (PMID 24391628, 2013). "In a well-characterized model of HIV-1 infection in human MDM, we have shown that IFN-α treatment or HIV-1 infection of MDM activates STAT1 phosphorylation to bind to and upregulate the GLS1 promoter activity, and subsequently increased glutaminase and glutamate production." (PMID 22479354, 2012).
HIV-1 infection (continued). "Regulation of the GLS1 promoter by IFN-α or HIV-1 infection is specific to STAT1 because when we used STAT3 antibody in the ChIP assay we found that neither IFN-α nor HIV-1 infection significantly increased binding between STAT3 and the GLS1 promoter (data not shown)." (PMID 22479354, 2012). "Studies have reported that the JAK/STAT signaling pathway could be inhibited by HIV-1 viral gene products, which involve Vif, Vpu, Nef, and Tat, in order to avoid the immune system; however, HIV-1 infection increases STAT-1 expression and overall phosphorylation." (PMID 37840143, 2023). "Interestingly, GLS1 promoter is also regulated by STAT1 under IFN-α stimulation or HIV-1 infection." (PMID 24086752, 2013). "Investigations on the phosphorylation status of STAT1, STAT2 and IRF9 in chronic HIV-1 infection are underway." (PMID 33064743, 2020). "Together, these data indicate that both HIV-1 infection and IFN-α treatment increase glutaminase expression through STAT1 phosphorylation and by binding to the GLS1 promoter." (PMID 22479354, 2012). "In addition, significant changes were observed in the expression of coding genes involved in the host response to infection (e.g., ISG15, STAT1, OAS3, ISG20, CCL2, and MX1), confirming robust HIV-1 infection of these cells." (PMID 31551335, 2019). "More importantly, IFN-α and IFN-β neutralizing antibodies, which were able to block the binding of type I IFNs with their receptor IFNR and the downstream STAT1 phosphorylation (60% reduction, ), significantly attenuated both mRNA and protein levels of GAC induced by HIV-1 infection." (PMID 22479354, 2012). "We also noted that HIV-1 infection induces a prominent antiviral state in early/mid-gestation HCs, characterized by transcription and secretion of IFN-α and significantly elevated transcription of the RLRs, STAT1, STAT5, ISG15, OAS1, IFIT1, IFIT2, IFIT3, and Viperin." (PMID 34432853, 2021). "Furthermore, total STAT1 is upregulated with longer treatment of IFN-α (data not shown) or HIV-1 infection and there was more precipitated promoter sequence using STAT1 antibody compared with IgG control, indicating un-phosphorylated STAT1 may bind with human GLS1 promoter in both sites 2/3 and 5/6." (PMID 24086752, 2013).
liver cancer (18 papers, 2016 to 2025). An epithelial or non-epithelial malignant neoplasm that arises from the liver. "The aberrant expression of HKDC1 has been associated with patient survival outcomes, with its role in liver cancer progression involving upregulating the expression of PD-L1 through STAT1 activation in tumor cells." (PMID 40909948, 2025). "Focusing on the expression of STAT1, notably, the inhibition of MYC in liver cancer is linked to elevated STAT1 expression, which upregulates PD-L1 and contributes to immune escape by tumor cells." (PMID 40909948, 2025). "Stat1 exhibits dual roles in liver cancer, activating tumor suppression pathways while also facilitating tumor angiogenesis, immune evasion, and drug resistance." (PMID 39160159, 2024). "IFIT3 can enhance the anti-liver cancer effect of IFN-α by binding transcriptional activators STAT1 and STAT2." (PMID 38753689, 2024). "By using two independent siRNAs against STAT1, its mRNA expression was depleted >90% in the different liver cancer cell lines." (PMID 35267462, 2022). "To assess the interplay of STAT1 and STAT3 protein in liver cancer cells, we first investigated the effect of STAT1 protein knockdown in the three liver cancer cell lines HepG2, HuH1, and HuH7, which all express the STAT1 and STAT3 proteins." (PMID 35267462, 2022). "The results showed that TKT is transported to the nuclei of liver cancer cells by interacting with the signal transducer and activator of transcription-1 (STAT-1)." (PMID 33520706, 2020). "Thus, the IFN-γ/JAK/STAT1/NK2R pathway is critical in inhibiting the advancement of liver cancer by enhancing the antitumor immune response through CD8+ T cell cytotoxicity." (PMID 40909948, 2025). "STAT1 has the strongest correlation with immune infiltrating cells, regulating the immune microenvironment, and thus affects the clinical outcome of patients with liver cancer." (PMID 35646925, 2022). "Moreover, in liver cancer both high miR203-expressing and low STAT1-expressing patients had a significantly longer survival than low miR203 expressing patients and high STAT1-expressing patients." (PMID 27705947, 2016). "Additionally, the regulation of HHLA2 expression by the IFN-γ/STAT1 pathway has only been observed in liver cancer; further investigation is required to explore the potential therapeutic effects of targeting this pathway to regulate HHLA2 expression in other gastrointestinal tumors." (PMID 40909948, 2025). "Research indicates that in liver cancer, IDO1 expression is upregulated by IFN-γ through the JAK1/STAT1 signaling, which undermines T cell functionality, aiding in the immune escape of tumors." (PMID 40909948, 2025). "In liver cancer, [pIC] also activates the IFN-γ/STAT1 pathway, resulting in significant antitumor effects." (PMID 40909948, 2025). "In liver cancer, HKDC1 and atorvastatin have been identified as modulators of STAT1, influencing downstream PD-L1 expression and consequently affecting tumor progression." (PMID 40909948, 2025). "Recent studies have reported that sodium butyrate, a differentiation inducer, arrested cell proliferation and strengthened the anti-tumor efficacy of IFN-α in liver cancer by specifically activating STAT1 and enhancing IFN-α-mediated STAT1 expression." (PMID 38273295, 2024). "For instance, in liver cancer, F2R influences the efficacy of PD-1 immunotherapy through the JAK2/STAT1 signaling pathway." (PMID 39655193, 2024). "As we found that IL-6 induces STAT1 transcriptional activity upon STAT3 depletion, we next sought to analyze the expression of STAT1 and STAT3 regarding infiltrating immune cells in human liver cancer tissues." (PMID 35267462, 2022).